BRAF (B-Raf proto-oncogene, serine/threonine kinase)
Diseases named in the same sentence as BRAF in open-access papers (continued):
Sharing a sentence is not in itself a finding about the gene and the disease.
melanoma (continued). "BRAF-mutant melanoma cells can become resistant to BRAF/MEK inhibitors after long-term exposure." (PMID 38336727, 2024). "Furthermore, PLX4720 is a selective BRAF inhibitor that upregulates BimS isoform expression to mediate BRAF V600E melanoma cell apoptosis." (PMID 38462618, 2024). "Collagen DDR receptors have also shown promise as targets for therapy, especially in combination approaches such as with BRAF inhibitors, which may improve melanoma treatment and reduce drug resistance of cancer cells." (PMID 39594665, 2024). "Indeed, MAPK14 is up-regulated in BRAF-inhibition-resistant melanoma in mouse models, while MAPK11 abrogation promotes radiosensitivity in A549, MCF7, and HCT-116 cells." (PMID 39666682, 2024). "To explore whether ROS induction mediated by trametinib plus CuET is essential for the upregulation of JUN in BRAF WT melanoma cells, we analyzed JUN expression following treatment with the combination in the presence of the ROS scavenger NAC." (PMID 38263136, 2024). "Additionally, CTCs were demonstrated to act as biomarkers for monitoring responsiveness to BRAF-targeted therapy in advanced melanoma patients." (PMID 38398206, 2024). "For instance, mutations in MAPK pathway components like rat sarcoma (RAS) and v-raf murine sarcoma viral oncogene homolog B1 (BRAF) genes (up to 40% mutations in human tumors such as thyroid cancer and melanoma, lung cancer and pancreatic cancer) contribute to drug resistance." (PMID 38254735, 2024). "In addition, both BET degrader as well as TCF4 knockdown sensitized melanoma cells to BRAF and MEK inhibitors in vitro." (PMID 38561348, 2024). "For instance, stromal cells including fibroblasts could mediate resistance to RAF inhibitors in BRAF‐mutant melanoma by secreting HGF and activating MAPK and PI3K signaling pathways in tumor cells." (PMID 39184861, 2024). "Unlike BRAF mutants, melanoma harboring an NRAS mutation alters GTP hydrolysis to consequently activate the MAPK, PI3K, and RAS-like protein guanine nucleotide exchange factor (GEF) signaling pathways." (PMID 38732242, 2024). "Furthermore, despite the documented OXPHOS inhibition by BRAF, many melanoma cells present a higher OXPHOS phenotype." (PMID 38254853, 2024). "To explore which ion channel(s) may be responsible for the abundance of plasmalemma Ca2+ flux, we visualized expression changes of specific genes in BRAF-mutant melanoma cell lines in the idling drug-tolerant state (8 days under BRAFi conditions)." (PMID 39001489, 2024). "Furthermore, targeting of the CoREST complex with the small-molecule inhibitor corin led to increased expression of DUSP1, inhibition of p38 MAPK activity, and resensitization of BRAF-resistant melanomas to BRAFi therapy." (PMID 38300709, 2024). "Thirdly, it is important to consider the lack of HER2 amplification or mutation models in BRAF-mutant melanoma and the absence of a direct comparison between RC48, T-DM1, and T-DXd in both in vitro and in vivo models." (PMID 38594618, 2024). "The current literature also highlights that half of the primary BRAF-mutated melanomas exhibit the non-brisk phenotype, while approximately 30% fall within the TIL brisk group." (PMID 38396984, 2024). "Personalized therapy in melanoma encounters a significant challenge due to the lack of precise diagnostic markers, especially in the context of BRAF/NRAS-driven melanomagenesis." (PMID 39582535, 2024). "A multicenter real-world study of the German Dermatologic Cooperative Oncology Group explored RFS, overall and melanoma-specific survival (MSS) and the response to subsequent treatment in 589 stage III melanoma patients undergoing adjuvant treatment with PD1 inhibitors or with BRAF+MEK inhibitors." (PMID 39727691, 2024). "Since most melanomas are BRAF mutations, NRAS mutations are rare, and not all cases have been analyzed for genetic testing; the information available is limited." (PMID 39650061, 2024).
melanoma (continued). "This study assessed the 3-year recurrence-free survival and overall survival of patients with melanoma, including the acral and mucosal subtypes, treated with anti-PD-1 antibody (Ab) or with the combination of the BRAF and MEK inhibitors dabrafenib and trametinib." (PMID 39123482, 2024). "In melanoma, we observed an overlap for gene signatures enriched in Class 2/3 BRAF mutant tumors at the transcriptional and genomic level—these included PI3K/AKT Signaling, Estrogen Response (Early and Late), Mitotic Spindle, G2M Checkpoint, and UV Response Dn." (PMID 38275886, 2024). "NF1 co-mutations with either BRAF or NRAS, as well as frequently with other melanoma-associated oncogenes, suggest that this is overall a weaker oncogenic driver that may cooperate with additional MAPK pathway alterations to drive melanomagenesis." (PMID 38611025, 2024). "Targeting BCL‐xL‐/BCL‐2 could sensitize tumour‐resistant cells to EGFR inhibitors, or result in the inhibition of actin remodelling molecules counteracting adaptive resistance to BRAF inhibitors in melanoma." (PMID 38693863, 2024). "The expression trend was similar and followed the immunohistochemistry results: the highest SNAI1 mRNA expression was observed in BRAF+ and BRAF– melanomas, supporting the role of SNAI1 as a potent epithelial repressor that cancer cells activate to detach from neighboring cells." (PMID 39273022, 2024). "For example, vemurafenib promotes cell cycle arrest at the G0/G1 phase and causes apoptosis in melanoma-sensitive, but not in melanoma-resistant, cell lines harboring the BRAF V600E mutation." (PMID 39000097, 2024). "On the other hand, BRAF mutations are detected in approximately 80% of nevi, which could undermine the role of BRAF alterations in melanoma development and progression." (PMID 39735251, 2024). "Naporafenib, a RAF dimer selective inhibitor, in combination with the MEK inhibitor trametinib or in combination with the ERK inhibitor LTT462, is being explored in a clinical trial for its efficacy in advanced metastatic KRAS- or BRAF-mutant NSCLC or in NRAS-mutant melanoma (NCT02974725)." (PMID 38731852, 2024). "Therefore, it would be more beneficial combining anti-PD1/L1 with another anti-cancer agent, such as chemotherapy for SCLC and TNBC, with TKI for RCC and HCC, and with anti-LAG3 or a BRAF/MEK inhibitor for melanoma." (PMID 38539487, 2024). "Moreover, depletion of MAP3K3 decreased the tumorigenic potential and BRAF inhibitor resistance of melanoma cells." (PMID 38622197, 2024). "RAC1P29S status in melanoma may therefore represent an important predictive biomarker for both response to targeted drugs against BRAF and MEK resistance and to ICIs." (PMID 40396280, 2024). "Patients with BRAF V600 mutations, which occur in approximately 40%–50% of patients with advanced melanomas, may receive targeted therapy with BRAF/MEK inhibitors." (PMID 39624750, 2024). "The first BRAF inhibitor, vemurafenib, was approved in the USA in 2011 following the results of a phase 3 trial (BRIM‐3) comparing it to dacarbazine in BRAF‐mutated melanoma." (PMID 38087810, 2024). "However, in clinical care of melanoma, BRAF and MEK inhibitors are strictly used in combination, while dabrafenib monotherapy is a rare exception." (PMID 39165562, 2024). "Thus, numerous studies have explored the effect of adjuvant therapies based on ICIs or targeted therapy (in BRAF-mutant melanomas) and have shown a consistent improvement in PFS and RFS, but not OS, compared to the placebo." (PMID 39727691, 2024). "Indeed, we have demonstrated that miR-579-3p transfection or, alternatively the exposure to MAPK inhibitors induce a block of proliferation and senescence programs in BRAF-mutant melanoma cells." (PMID 38472212, 2024). "Also, BRAF inhibitors, which have demonstrated efficacy in other cancers like melanoma, are being explored as potential therapeutic options in LGSOCs." (PMID 39409889, 2024).
melanoma (continued). "The PI3K-AKT pathway plays a significant role in BRAF-/MEK-inhibitor resistance in melanoma patients and may represent a crucial target for combination therapy." (PMID 38247727, 2024). "Furthermore, both Y27632 and fasudil were able to restore the efficacy of BRAF inhibitors in resistant melanoma cells." (PMID 39273383, 2024). "This combination therapy displayed promising anti-tumor activity, particularly in patients with advanced BRAF(V600)-mutated melanoma without a BRAFi." (PMID 39582535, 2024). "Similarly, in BRAF-mutant melanoma models treated with BRAF/MEK inhibitors, the next-generation pan-BET inhibitor PLX51107 suppresses adaptive receptor tyrosine kinase upregulation in response to targeted therapy." (PMID 38473997, 2024). "In BRAF mutant melanoma cells, the STAT3 pathway is directly activated by PI3K-AKT." (PMID 38534309, 2024). "Patients with concurrent (or sequential) BRAF-mutant melanoma and HCL have been described." (PMID 39467959, 2024). "This has led to extensive studies on the combination of various small-molecule drugs, including epidermal growth factor receptor inhibitors in esophageal squamous cell carcinoma, BRAF or MEK inhibitors in melanoma, ALK inhibitors in neuroblastoma, and immune checkpoint inhibitors." (PMID 39000513, 2024). "Notably, in contrast to ICIs for unresectable melanoma, the efficacy and safety profiles of BRAF/iMEKi combination therapy in Japan are comparable to those in Caucasian countries." (PMID 39337055, 2024). "Although our patient did not have BRAF mutation, which is the most common mutation identified in malignant melanoma, he was found to have TERT mutation." (PMID 39258061, 2024). "In vivo, endothelial-restricted BRAF knockout mice show a reduced extravasation of B16F10 melanoma cells in the lung vasculature after tail vein injection, and that might indicate the role of BRAF in the regulation of metastatic spreading." (PMID 39457016, 2024). "Melanoma treatment showed good efficacy when administered in the early stage after the application of BRAF inhibitors (BRAFis), but drug resistance and recurrence sometimes occur when these agents are administered in a later stage, and the pathways involved in this drug resistance are diverse." (PMID 39161800, 2024). "Interestingly, an increase in pDC recruitment was observed in BRAFV600E melanomas compared to BRAF wild-type melanomas." (PMID 39020402, 2024). "Advanced melanoma patients with NRAS and BRAF mutations respond better to treatment." (PMID 39195270, 2024). "BRAF/RAS mutations and TERT promoter mutations commonly coexist to form genetic duets that drive poor clinical outcomes of PTC and hence are the main players in current genetic-based risk management of PTC and some other cancers as well, such as melanoma." (PMID 38735658, 2024). "While rare, solid malignancies with BRAF fusion may be targeted by MEK inhibitors, based on a study evaluating trametinib in melanoma with non-V600E BRAF mutation or BRAF fusion, although additional study in other solid malignancies is needed." (PMID 38791902, 2024). "The leading molecular biomarker in the context of a targeted therapy in patients with melanoma is the presence of the BRAFV600 mutation, as the role of BRAF/MEK inhibitors is well established in adjuvant or palliative therapy in patients with BRAF-mutated tumors." (PMID 38540282, 2024). "Besides vemurafenib, two other BRAF inhibitors were approved for the treatment of advanced melanoma: dabrafenib, approved as monotherapy in 2013, and encorafenib, approved in 2018." (PMID 38339003, 2024). "In recent years, it has been identified that genetic factors, including activating mutations in the BRAF and NRAS oncogenes, contribute to melanoma initiation, promoting its growth and metastasis, as well as the transition of melanoma cells into different epithelial and mesenchymal states." (PMID 39099686, 2024).
melanoma (continued). "Despite several multi-tyrosine kinase and BRAF-specific inhibitors being FDA and EMA approved for BRAF-mutant THCA tumours they are less sensitive to these drugs than melanoma, rapidly developing resistance, and new treatment strategies continue to be evaluated, including combination therapies." (PMID 38304083, 2024). "On the other hand, pairs such as CCR1-CCL4 are always co-upregulated but with different prognostic values; i.e., they are associated to higher survival in melanoma (RAS and BRAF hotspot mutant subtypes), and to lower survival in genomically stable gastric cancer (GI.GS subtype)." (PMID 38723607, 2024). "Similarly, the COMBI-AD trial investigated the effects of dabrafenib (a BRAF inhibitor) plus trametinib (a MEK inhibitor) on patients with resected BRAFV600-mutant stage III melanoma, including those with in-transit metastases." (PMID 39272923, 2024). "Loss of NF1 function co-occurres also with the mutated BRAF and NRAS melanomas." (PMID 39340537, 2024). "Of these factors, multicenter retrospective studies in Japan attempted to address whether patients with BRAF V600‐mutant melanoma, acral/mucosal subtypes of melanoma, and non‐acral/mucosal BRAF wild‐type melanoma should receive Nivo/Ipi upfront." (PMID 38358050, 2024). "Furthermore, after monotherapy with BRAF inhibitors was first trialled in melanoma, the eruptive development of other MAPK-driven neoplasms (most commonly RAS mutant keratoacanthomas and cutaneous squamous cell carcinomas) was reported." (PMID 38804700, 2024). "High‐CSD melanoma frequently harbors NRAS, BRAF non‐V600E, and KIT mutations." (PMID 39564955, 2024). "The large majority (93%) of patients treated with targeted therapy had BRAF-mutant melanomas." (PMID 39727691, 2024). "Importantly, both BRAFV600-mutant and BRAF-WT melanoma patients benefited from relatlimab plus nivolumab treatment compared to nivolumab alone (HR 0.76 and 0.83, respectively)." (PMID 39727691, 2024). "Based on the current knowledge, we try to answer the question of whether other melanoma genomic tests can enrich current BRAF diagnostics in the clinics." (PMID 39340537, 2024). "Mutations in NRAS and BRAF genes, seen in a significant proportion of melanoma cases, lead to dysregulated signaling and persistent ERK activation, promoting cancer cell growth, melanoma development, and immune evasion." (PMID 39519202, 2024). "So, it—resistance [against a treatment] develops very quickly in the vast majority of people with BRAF inhibitors [drugs targeting the BRAF protein that might play a role in some tumors, including some melanomas]." (PMID 39176222, 2024). "BRAF inhibitors in combination with MEK inhibitors resulted in increased tolerability and efficacy, leading to several combination therapies being improved (dabrafenib plus trametinib, vemurafenib plus cobimetinib, and encorafenib plus binimetinib) in BRAF V600E-mutant melanoma." (PMID 39337530, 2024). "The proportion of this population can be increased by treatment with a BRAF inhibitor (BRAFi) or BRAFi plus a MEK inhibitor (MEKi), designed to target the common BRAF mutations in melanoma that activate MAPK signalling, suggesting this population plays a crucial role in drug resistance." (PMID 39092608, 2024). "Overall, our review is distinguished by its comprehensive approach that bridges the gap between preclinical research, clinical application, FDA-approved therapies, immunotherapy integration, and innovative markers in the context of BRAF-targeted treatment for melanoma." (PMID 39582535, 2024). "Only 1 BRAF-mutant and 1 BRAF–wild type melanoma had duplication events overlapping CDKN2A." (PMID 38758740, 2024). "BRAF inhibitors such as dabrafenib, encorafenib, and vemurafenib focus on melanoma and NSCLC with BRAF mutations, while Bruton tyrosine kinase inhibitors such as acalabrutinib and ibrutinib are used for mantle cell lymphoma and chronic lymphocytic leukemia, among others." (PMID 39337925, 2024).
melanoma (continued). "Meanwhile, the pivotal phase III randomized clinical trials including Keynote-054, CheckMate-238, and COMBI-AD have validated the efficacy of adjuvant therapy regimens in resected stage III melanomas, comprising immunotherapy (IT) or targeted therapy (TT) in BRAF-mutant melanomas." (PMID 39274453, 2024). "Multiple features of the TME in BRAF-mutant melanomas have been characterized." (PMID 39336897, 2024). "In a report on melanoma, the inhibition of V600EBRAF decreased WEE1 expression, suggesting that WEE1 is located downstream of V600E BRAF in the MAPK signaling cascade and that mutations in BRAF activate the MAPK pathway and increase WEE1 expression." (PMID 39335109, 2024). "Out of 175 patients, 150 had no previous melanoma diagnosis, and 52% (78 patients) of these patients had a BRAF mutation." (PMID 39200941, 2024). "IC50 values of Everafenib and Everafenib–CO2H against BRAF-sensitive melanoma cell lines." (PMID 38256937, 2024). "BRAF + subtype commonly manifests as superficial spreading melanoma on the trunk." (PMID 39340537, 2024). "Vemurafenib is one of the substrates of ABCG2, and it was suggested that this transporter could influence BRAF resistance acquisition in melanoma cells." (PMID 39175042, 2024). "Indeed, we did not identify any genes that were significantly enriched in Class 3 BRAF mutant metastatic vs. primary melanoma tumors." (PMID 38275886, 2024). "These tumors exhibit unique histological features, including a biphasic pattern with neurocristic and melanocytic components, as well as an absence of BRAF mutations commonly found in conventional melanoma." (PMID 39421096, 2024). "Triple WT melanomas are characterized by the absence of mutations in these three genes (BRAF, RAS, and NF1)." (PMID 39126091, 2024). "We therefore hypothesized that CoREST inhibition may elicit synergistic growth inhibition with BRAF inhibitor (BRAFi) therapies through epigenetic reprogramming of BRAF-mutant melanoma." (PMID 38300709, 2024). "The results verified alantolactone enhanced sensitiveness of BRAF mutant melanoma to MAPKi in vivo." (PMID 38822350, 2024). "In addition, double targeting effects on CDK4/6 and mutant-BRAF or MEK can regress strong and persistent melanomas with BRAF- and NRAS-mutations in preclinical studies." (PMID 38462618, 2024). "DREAMseq is a phase 3 clinical trial that included 256 patients with advanced BRAF-mutant melanoma." (PMID 38748192, 2024). "Treatment of malignant melanoma was a thorny problem decades ago, and now, due to the development of immunotherapy and the emergence of BRAF suppression methods, these treatments have been greatly improved; however, some malignant melanomas are still prone to recurrence or even metastasis." (PMID 39161800, 2024). "Additionally, the proportion of 37% of BRAF V600 mutated patients treated with pembrolizumab underscores the relevance of adjuvant immunotherapy in melanoma despite a given alternative of using BRAF/MEK-inhibitors in the adjuvant setting." (PMID 39517999, 2024). "Acral melanoma is characterized by higher rates of BRAF-wild type, lower tumor mutation burden, and a lack of ultraviolet (UV)-related mutational signatures compared to non-acral cutaneous melanoma." (PMID 39123482, 2024). "Considering that lentigo maligna (LM) is genetically different from melanoma that is linked to short-term sun exposure, BRAF mutations in LM are not as important." (PMID 39200941, 2024). "The fact that BRAF and NRAS genes were mutated in the analyzed advanced-stage NeM patients, suggests that the biology of NeM corresponds to that of classical melanoma, further supporting the interpretation of this melanoma as a diagnostic challenge, rather than a distinct biological entity." (PMID 39796694, 2024). "In melanoma tumor cell lines, we did not detect any other mutation apart from the expected BRAF V600E, MAP2K1 P124S (_f1), and NRAS Q61K mutations (Dataset EV 3)." (PMID 38898234, 2024).